ENSG00000282988 (novel protein)
Gene: Protein-coding gene on chromosome 6 (26,195,595 to 26,199,293, reverse strand). Ensembl gene ENSG00000282988.
Genetic constraint (gnomAD): Loss-of-function variants: 25 observed, 14.02 expected, observed/expected ratio (o/e) 1.78, 90% interval 1.25 to 1.97. The synonymous counts are far from expectation, so gnomAD's model fits this gene poorly and the ratio says little. Missense variants: 358 observed, 243.04 expected, observed/expected ratio (o/e) 1.47, 90% interval 1.35 to 1.61. Synonymous variants: 195 observed, 110.48 expected, observed/expected ratio (o/e) 1.76, 90% interval 1.57 to 1.95.